PDE4D (phosphodiesterase 4D)
Diseases named in the same sentence as PDE4D in open-access papers (continued):
Sharing a sentence is not in itself a finding about the gene and the disease.
asthma (continued). "In addition, we genotyped four SNPs that have been reported to be associated with asthma, rs7216389 in ORMDL3, rs11684634 in PDE11A, rs1544791 in PDE4D and rs2706347 in RAD50." (PMID 23046476, 2012). "We hypothesised that increased PDE4D in asthmatic airway smooth muscle was contributing to the β2AR “defect” observed in asthma." (PMID 21611147, 2011). "Therefore, PDE4D holds great potential as a drug target for childhood asthma treatment." (PMID 38730525, 2024). "Computational molecular docking of DCT compounds identified five proteins (ESR1, KDR, LTA4H, PDE4D and PPARG) mutually targeted by asthma genes and DCT compounds and 155 docking connections associated with cellular pathways involved in the biological mechanisms of asthma." (PMID 32185106, 2020). "Each of the five identified target proteins, ESR1, KDR, LTA4H, PDE4D and PPARG, have established potential to play significant roles involving both the primary and secondary asthma pathways through many signaling cascade pathways." (PMID 32185106, 2020). "The five identified target proteins, ESR1, KDR, LTA4H, PDE4D and PPARG, show evidence of involvement in the pathological expression of asthma, with three classified as receptors (ESR1, KDR, PPARG), and two categorized as enzymes (LTA4H, PDE4D) (KEGG, UniProt)." (PMID 32185106, 2020). "The secondary KEGG asthma disease pathway PI3K-Akt signaling pathway, involves PDE4D through the cAMP signaling pathway, leading to cell growth, survival and proliferation (KEGG)." (PMID 32185106, 2020). "Multiple genetic predispositions have been found in Hispanic populations including the role of PDE4D and PDE4 inhibitors, upon which medications have even been developed for asthma." (PMID 29686953, 2018). "This suggests that MICB, PDE4D, and IL‐21 proteins do not influence the occurrence of childhood asthma through BMI." (PMID 38730525, 2024). "This suggests that MICB, PDE4D, and IL‐21 plasma proteins do not influence the occurrence of childhood asthma through BMI." (PMID 38730525, 2024). "Furthermore, we found no deletions or duplications nominally associated with asthma symptoms in loci consistently associated with the disease in previous studies, including: DENND1B, IL1RL1, PDE4D, TSLP, IL13, HLA-DR/DQ and IL33 regions." (PMID 30262839, 2018).
ischemic stroke (21 papers, 2005 to 2025). A stroke disorder caused by obstruction of blood flow to the brain, due to thrombotic (local blood clot formation) or embolic (due to a blood clot or other material traveling from another site) event. "The PDE4D gene has been demonstrated to have a positive correlation with the risk of ischemic stroke." (PMID 39897494, 2025). "Several studies have shown a robust association of PDE4D variants with ischemic stroke in young individuals." (PMID 36973604, 2023). "Numerous case–control studies have been performed to assess the association between PDE4D variants and ischemic stroke risk among different ancestral populations." (PMID 36973604, 2023). "In published research that includes genome-wide association studies and meta-analyses, the phosphodiesterase 4D (PDE4D) rs966221 variant has been identified as a risk factor in ischemic stroke (IS) in the Caucasian population." (PMID 37508970, 2023). "For example, in the Chinese population, both SNP83 and SNP87 of the PDE4D gene have been reported to confer a greater risk of developing ischemic stroke." (PMID 34206420, 2021). "Among women, 4 phosphodiesterase 4D SNPs were associated with both higher and lower ischemic stroke risk, after stratification by hypertension status." (PMID 31127075, 2019). "It has been demonstrated that phosphodiesterase 4D (PDE4D) genetic polymorphism is associated with ischemic stroke." (PMID 28225001, 2017). "In the present study, we evaluated the association of PDE4D with 3-month outcome after ischemic stroke in a Chinese population." (PMID 28225001, 2017). "We found that the SNP87 genotype in PDE4D was associated with an increased risk of 3-month unfavorable outcome after ischemic stroke under the additive and recessive models." (PMID 28225001, 2017). "In order to reduce heterogeneity from these confounding factors, we focus our attention on the association between SNP 83 in PDE4D gene and ischemic stroke in Chinese population." (PMID 23799094, 2013). "Meta-analysis of case-control studies on the relationship between SNP 83 in PDE4D gene and susceptibility to ischemic stroke in Chinese population published domestically and abroad from January 2003 to September 2012." (PMID 23799094, 2013). "The SNP 83 in PDE4D gene has been suggested as a risk factor in ischemic stroke, but direct evidence from genetic association studies remains inconclusive even in Chinese population." (PMID 23799094, 2013). "How can we explain the association between SNP 83 in PDE4D gene and ischemic stroke in Chinese population?" (PMID 23799094, 2013). "The association between PDE4D and ischemic stroke was confirmed for allele C homozygote of SNP 83 (OR = 1.42, 95% CI: 1.14–1.77) but not in the carriers (OR = 1.20, 95% CI: 0.97–1.47)." (PMID 23799094, 2013). "Well-designed case-control studies with large sample sizes regarding the association of SNP 83 in PDE4D gene and ischemic stroke need to be performed on different ethnic population in the future." (PMID 23799094, 2013). "In conclusion, our meta-analysis suggests that SNP 83 in PDE4D gene is associated with developing ischemic stroke in Chinese population." (PMID 23799094, 2013). "The results suggest that SNP 83 in PDE4D gene is significantly associated with susceptibility to ischemic stroke in Chinese population." (PMID 23799094, 2013). "Furthermore, numerous case–control studies have demonstrated a correlation between PDE4D variants and the risk of ischemic stroke across diverse ethnic groups." (PMID 41464128, 2025). "In addition, more extensive research is needed to identify a potential significant association between PDE4D gene variants and ischemic stroke risk." (PMID 34206420, 2021). "The four studies identified here found that four phosphodiesterase 4D SNPs were associated with ischemic stroke after stratification by hypertensive status, pTG was associated with increased risk of ischemic stroke and an association between two F12 SNPs were associated with pTG." (PMID 31127075, 2019).
ischemic stroke (continued). "First, ischemic stroke manifests different pathogenesis, and the PDE4D gene may be associated with a specific subtype." (PMID 28225001, 2017). "Similarly, human PDE4D haplotypes and single-nucleotide polymorphisms (SNPs) correlate with ischemic stroke, and PDE4B SNPs are associated with schizophrenia." (PMID 29088834, 2017). "Therefore, we have conducted this meta-analysis in order to derive a more convinced result between SNP 83 in PDE4D gene and susceptibility to ischemic stroke in Chinese population." (PMID 23799094, 2013). "Several epidemiologic studies found an association between PDE4D gene and ischemic stroke." (PMID 21151982, 2010). "However, variation in PDE4D was recently reported to be associated with the risk of ischemic stroke." (PMID 15752431, 2005). "Notably, among women without hypertension, the SNPs rs9 (HR=0.48; 95% CI, 0.26-0.91), rs42 (HR=1.73; 95% CI, 1.10-2.70), rs219 (HR=1.73; 95% CI, 1.13-2.64), and rs220 (HR=1.56; 95% CI, 1.05-2.32) of the phosphodiesterase 4D gene were associated with ischemic stroke." (PMID 31127075, 2019). "Therefore, in this study we aimed to investigate the association of PDE4D genetics with 3-month outcome after ischemic stroke, and its different subtypes classified by the Trial of Org10172 in Acute Stroke Treatment (TOAST) classification in a Chinese population." (PMID 28225001, 2017). "Several studies have investigated the correlation between phosphodiesterase 4D (PDE4D) single nucleotide polymorphism (SNP) rs918592 and the risk of ischemic stroke (IS) in Chinese populations." (PMID 38172709, 2024). "Both the phosphodiesterase 4D and AC008828-2 genes have been studied extensively with research showing their positive association with ischemic stroke risk." (PMID 31127075, 2019). "Two studies analyzed single nucleotide polymorphisms (SNPs) in the phosphodiesterase 4D and AC008828-2 genes and risk of ischemic stroke." (PMID 31127075, 2019). "However, the association between PDE4D gene and prognosis after ischemic stroke remains unknown." (PMID 28225001, 2017). "To clarify the varying results, we have undertaken this meta-analysis of SNP 83 in PDE4D gene and ischemic stroke in Chinese population." (PMID 23799094, 2013). "Subgroup analysis was performed for SNP 83 in PDE4D gene and ischemic stroke in Chinese population by the subtypes of ischemic stroke." (PMID 23799094, 2013). "Our findings suggest three genes (PDE4D, ACE I/D and IL10) to have statistically significant ORs for risk of ischemic stroke in a South Asian adult population and the totality of data supported MTHFR C677T as a further likely risk factor." (PMID 23505425, 2013). "The PDE4D SNP83 polymorphism was investigated in three studies covering Pakistan and North India in a total of 1338 subjects (626 Ischemic stroke cases; 712 controls)." (PMID 23505425, 2013). "Several studies have reported a positive or null relation between SNP 83 in PDE4D gene and ischemic stroke in Chinese population, but findings have been controversial." (PMID 23799094, 2013). "For example, prior associations of several of the candidate genes with related clinical disease phenotypes (for example, PDE4D with ischemic stroke, SORL1 with AD) have described allelic heterogeneity." (PMID 17903297, 2007). "According to the literature review, the core proteins identified, such as Adk, Aprt, Entpd1, and Pde4d, are closely related to the pathogenesis and treatment of ischemic stroke, opening a new path and providing solid theoretical support for the subsequent exploration of pharmacodynamic mechanisms." (PMID 39942654, 2025). "Ischemic stroke patients were found to express reduced total PDE4D levels in their Epstein-Barr virus (EBV)-transformed B cell lines compared to healthy individuals because of significantly reduced expression of the PDE4D gene isoforms: PDE4D1, PDE4D2, and PDE4D5." (PMID 34206420, 2021).
ischemic stroke (continued). "Several meta-analyses have been published that contradict these findings by stating that no genetic variants of the PDE4D gene can be significantly linked to ischemic stroke." (PMID 34206420, 2021). "In addition, it has been reported that the PDE4D gene is involved in ischemic stroke pathogenesis through differential expression of the PDE4D gene isoforms." (PMID 34206420, 2021). "Moreover, phosphodiesterase 4D (PDE4D), and 5-lipoxygenase gene activating protein (ALOX5AP), were shown to be significantly related with ischemic stroke due to progressive changes in the walls of blood vessels resulting in the increased atherosclerosis process." (PMID 30305144, 2018).
schizophrenia (19 papers, 2009 to 2024). A major psychotic disorder characterized by abnormalities in the perception or expression of reality. "Directly relevant to the current study, single-nucleotide polymorphisms (SNPs) in PDE4D that decrease mRNA expression are associated with increased risk of schizophrenia and cognitive impairment in mental illness." (PMID 33328902, 2020). "In addition, a study of a Finnish population found two PDE4D variants to be highly associated with schizophrenia, possibly with a regulatory function based on their location in an intronic region within the gene." (PMID 38790238, 2024). "Genetic variation in both genes, FOXP2 and PDE4D, was previously associated with schizophrenia." (PMID 36192459, 2022). "Rs17382202 is in the phosphodiesterase 4D (PDE4D) gene, encoding for a key enzyme in nitric oxide neurotransmission, whose role in the pathogenesis of schizophrenia is under investigation." (PMID 38523642, 2024). "For example, PDE4D and schizophrenia (SCZ) (odds ratios (OR) = 1.0531, PIVW = 0.0414), as well as major depressive disorder (MDD) (OR = 1.0329, PIVW = 0.0011)." (PMID 37605207, 2023). "Studies have demonstrated therapeutic benefits of PDE4D inhibitors in the treatment of Alzheimer’s disease, Huntington’s disease, schizophrenia, and depression." (PMID 37775746, 2023). "The current study interrogated the subcellular localization of PDE4D in young rhesus macaque dlPFC layer III, the circuits which underlie higher cognition and are a key locus of pathology in schizophrenia and Alzheimer’s disease." (PMID 33328902, 2020). "Genetic variation in PDE4B has been linked to schizophrenia, while ACRYDS2 mutations in PDE4D severely affect cognitive function." (PMID 30800055, 2019). "We next explored whether PDE4A, PDE4B, PDE4C, and PDE4D are differentially expressed not only in the brain samples but also in blood samples of patients with schizophrenia and thus might serve as biomarkers." (PMID 38790238, 2024). "PDE4D inhibitors may also be useful for the treatment of psychiatric disorders in which cognition is impaired including schizophrenia, bipolar disorder, and major depression." (PMID 30131563, 2018). "Ependymal nuclei exhibited the largest number of DEGs, including reduced PDE4D and increased FOXP2 expression in schizophrenia." (PMID 36192459, 2022). "The ependymal cluster exhibited the largest number of DEGs between schizophrenia and controls, including reduced PDE4D, and increased FOXP2 and EML6 expression activity in schizophrenia." (PMID 36192459, 2022). "Recently, small-molecule allosteric modulators of PDE4D that do not completely inhibit enzymatic activity were reported to reduce emesis and to have therapeutic benefit for brain distribution, such as Alzheimer's disease, Huntington's disease, schizophrenia, and depression." (PMID 21437195, 2011). "Recently, small-molecule allosteric modulators of PDE4D that do not completely inhibit enzymatic activity were reported to reduce emesis and have therapeutic benefits of a brain distribution, for such entities as Alzheimer's disease, Huntington's disease, schizophrenia, and depression." (PMID 22074248, 2011).
Alzheimer disease (18 papers, 2007 to 2025). A progressive, neurodegenerative disease characterized by loss of function and death of nerve cells in several areas of the brain leading to loss of cognitive function such as memory and language. "In particular, PDE4D has been associated with Alzheimer’s disease and the intellectual disability seen in fragile X syndrome." (PMID 38983619, 2024). "PDE4D alters the function of calcium channels in the central nervous system and is considered one of the causes of Alzheimer’s disease (AD)." (PMID 31941117, 2020). "Inhibition of phosphodiesterase 4D (PDE4D) enzymes has been investigated as therapeutic strategy to treat memory problems in Alzheimer’s disease (AD)." (PMID 37306762, 2023). "PDE4D constitutes a high-interest therapeutic target primarily for the treatment of Alzheimer’s disease, as it is highly involved in neuroinflammation, learning ability, and memory dysfunctions." (PMID 33806914, 2021). "We firmly believe that this research will assist in the design and development of novel PDE4D small molecule inhibitors with fewer side effects and a wider therapeutic window for the treatment of Alzheimer’s disease." (PMID 33806914, 2021). "Notably, PDE4D Inhibitors are in clinical trials for the treatment of Alzheimer’s disease and Fragile X syndrome." (PMID 35089962, 2022). "Although natural products may target multiple proteins, PDE4D certainly represents an important target in the treatment of neurological disorders, such as Alzheimer’s disease." (PMID 33806914, 2021). "Phosphodiesterases (PDEs) have long been considered as targets for the treatment of Alzheimer's disease (AD) and a substantial body of evidence suggests that one sub-family from the super-family of PDEs, namely PDE4D, has particular significance in this context." (PMID 31642904, 2019). "However, surprisingly few genes have been identified that determine the risk of developing stroke (PDE4D, ALOX5AP) or Alzheimer's disease (APOE4), in the community as a whole, that is for persons not from autosomal dominant, early-onset families." (PMID 17903297, 2007). "Moreover, our inverse docking results showed that curcumin potentially binds also to the proteins cAMP-specific 3′,5′-cyclic phosphodiesterase 4D and 17-β-hydroxysteroid dehydrogenase type 10, which provides a new explanation for its efficiency in the treatment of Alzheimer’s disease." (PMID 30567342, 2018). "In this respect, many partial PDE4D inhibitors, namely, BPN14770, MK-0952, GEBR-32a, and chlorbipram, have been developed and tested in the clinical trials for the treatment of Alzheimer’s disease." (PMID 33806914, 2021).
depression (16 papers, 2011 to 2025). "The gap between this promising pharmacotherapeutic target and the pathophysiology of depression hampers the development of PDE4D variant-selective inhibitors into novel antidepressants." (PMID 26161529, 2015). "Thus, our findings could benefit the structure- and scaffold-based design of PDE4D variant-selective inhibitors with high therapeutic indices for treatment of depression and disorders with memory deficits." (PMID 26161529, 2015). "Animal research also reported that Pde4d-KO mice exhibited decreased immobility in tail suspension and forced swim tests, which suggested that PDE4D plays a role in the pathophysiology and pharmacotherapy of depression." (PMID 38255289, 2024). "Similarly, Pde4d KO mice demonstrate reduced immobility in behavioral despair models, which may relate to depression and affective symptoms occasionally co-occurring in ASD." (PMID 41155624, 2025). "In addition, PDE4D seems to be involved in depression, with PDE4DIs able to reverse the depression-like behaviors induced by chronic unpredictable stress (CUS) through restoring cAMP, PKA, the phosphorylation of CREB (pCREB), and GLT1 (glutamate transporter 1) levels in the hippocampus of rats." (PMID 39125619, 2024). "Pde4d-KO mice exhibit decreased immobility in tail suspension and forced swim tests, suggesting that PDE4D may play a role in the pathophysiology and pharmacotherapy of depression." (PMID 33414502, 2021). "PDE4D has been etiologically implicated in the pathogenesis of other neuropsychiatric diseases associated with PFC dysfunction, with genome-wide association studies identifying point mutations in PDE4D with intellectual disability, major depression and anxiety disorders." (PMID 33328902, 2020). "For example, PDE4D inhibition via miR-139-5p restored hippocampal neurogenesis and upregulated cAMP/PKA/CREB/BDNF signaling in stress-induced depression models, highlighting its role in enhancing plasticity and antidepressant effects." (PMID 41155624, 2025). "PDE4D inhibition by D159687, on the other hand, did not induce any behavioral changes in mouse models of depression or anxiety, but improved cognition in the mouse NOR test, whereas as the PDE4B inhibitor had no procognitive benefit in healthy adult mice." (PMID 28054669, 2017). "Interestingly, in the current study, the PDE4D inhibitor does not affect behaviors related to depression or anxiety." (PMID 28054669, 2017).